RPE (ribulose-5-phosphate-3-epimerase)
Description:
Catalyzes the reversible epimerization of D-ribulose 5-phosphate to D-xylulose 5-phosphate.
Synonyms: RPE2-1
Tractability: Small molecule: a structure with a bound ligand is known; it has a binding pocket of medium quality. Antibody: the Human Protein Atlas places it where antibodies can reach. PROTAC: ubiquitination databases record sites on it; its protein half-life has been measured.
Gene: Protein-coding gene on chromosome 2 (210,002,565 to 210,022,262, forward strand). Ensembl gene ENSG00000197713.
Subcellular location (Human Protein Atlas): Cytosol; Nucleoplasm; Plasma membrane
Pathways (Reactome):
Metabolism: Pentose phosphate pathway
Gene Ontology:
Molecular function: D-ribulose-phosphate 3-epimerase activity; identical protein binding; metal ion binding; protein binding; protein homodimerization activity; racemase and epimerase activity, acting on carbohydrates and derivatives
Biological process: carbohydrate metabolic process; pentose-phosphate shunt; pentose-phosphate shunt, non-oxidative branch
Cellular component: extracellular exosome; cytosol
Genetic constraint (gnomAD): Loss-of-function variants: 16 observed, 24.57 expected, observed/expected ratio (o/e) 0.65, 90% interval 0.44 to 0.99. The upper end of that interval is the gene's LOEUF score, 0.99, which puts it in group 4 of 6, group 1 being the genes least tolerant of losing a copy. Missense variants: 240 observed, 302.54 expected, observed/expected ratio (o/e) 0.79, 90% interval 0.71 to 0.88. Synonymous variants: 93 observed, 101.6 expected, observed/expected ratio (o/e) 0.92, 90% interval 0.77 to 1.09.
Homologues: Orthologues: macaque RPE (100% identical), guinea pig Rpe (98% identical), mouse Rpe (97% identical), rat Rpe (97% identical), tropical clawed frog rpe (89% identical), chimpanzee RPE (88% identical), dog RPE (83% identical), zebrafish rpe (82% identical), Caenorhabditis elegans F08F8.7 (59% identical), Drosophila melanogaster Rpe (59% identical). Paralogues in human: RPEL1 (96% identical).
Diseases named in the same sentence as RPE in open-access papers:
RPE is named in the same sentence as 4 diseases in open-access papers, as found by Europe PMC text mining. Sharing a sentence is not in itself a finding about the gene and the disease. The quoted sentences say what the papers report.
pancreatic cancer (3 papers, 2020). "Ribulose 5-Phosphate 3-Epimerase (RPE) has been detected in pancreatic cancer, and its effect might be through the activation of fructose 2,6 bisphosphate (F-2, 6BP), which activates phosphofructose kinase 1 (PFK1), and/or K-ras." (PMID 32664469, 2020). "In this enhanced metabolic pathway, pancreatic cancer cells display increased ribulose 5-phosphate isomerase (RPIA) and ribulose-5-phosphate-3-epimerase (RPE) expression." (PMID 32122374, 2020). "The RPE enzyme belongs to the nonoxidative arm of the PPP, and its expression is regulated by KRAS in pancreatic cancers (PDAC)." (PMID 32365991, 2020).
lung carcinoma (1 paper, 2021). "These analyses demonstrated that mRNA expression of G6PD, glutaminase (GLS), hydroxy-prostaglandin dehydrogenase 15-(NAD) [HPGD], TKT, TALDO1, ribulose-5-phosphate-3-epimerase (RPE), and transketolase-like-1 (TKTL1) were more abundant in lung cancer patient samples." (PMID 34827081, 2021).
cancer (3 papers, 2016 to 2020). A tumor composed of atypical neoplastic, often pleomorphic cells that invade other tissues. "Among these essential genes is ribulose-5-phosphate-3-epimerase (RPE), which encodes a pentose phosphate pathway enzyme and whose role in cancer is still unclear." (PMID 32365991, 2020). "Notably, RPE (ribulose-5-phosphate-3-epimerase) is one of the Carbon Metabolism genes that show enhanced association with the Pathway in Cancer genes." (PMID 27363021, 2016). "In general, the associations between Carbon Metabolism and Pathway in Cancer genes become weaken in HCC, whereas the associations between a number of genes are enhanced, especially those in the 22 up-regulated carbon metabolism genes group (such as HK1, PGK1, ENO1, PGLS, RPE)." (PMID 27363021, 2016). "The genes ACLY, CS, RPE, and IDH2 were found to be among the top 10% of the genes that were frequently overexpressed across 19 cancer types from a meta-analysis study of 1981 tumors (FDR p value < 0.05)." (PMID 30823893, 2019).
RPE also shares sentences with these, for which no sentence is quoted: malaria (1 paper).